SIRT1 (sirtuin 1)
Diseases named in the same sentence as SIRT1 in open-access papers (continued):
Sharing a sentence is not in itself a finding about the gene and the disease.
renal fibrosis (continued). "Additionally, we studied the effect and possible mechanisms of AM and CZ in the treatment of CKD, the results showed that AM and CZ alleviated adenine-induced kidney dysfunction, inflammation, and renal fibrosis, which are related to SIRT1/JNK signaling pathway." (PMID 37089928, 2023). "SIRT1 activators could be developed to inhibit the apoptosis and senescence of kidney cells, reduce renal inflammation and oxidative stress, improve mitochondrial function, and reduce renal fibrosis." (PMID 35795148, 2022). "Therefore, the inhibition of NLRP3 inflammasome and activation of Sirt1 could be attractive targets to ameliorate renal fibrosis." (PMID 31118021, 2019). "Additionally, in patients with chronic kidney disease, SIRT1 activation could protect against renal fibrosis by inhibiting the TGF-β/Smad3 pathway." (PMID 30123131, 2018). "Sirtinol also blocked the inhibitory effect of losartan on the UUO-induced renal fibrosis, suggesting that the anti-fibrotic effect of losartan might be mediated at least in part through inhibition of ER stress via up-regulation of SIRT1, followed by induction of HO-1 and thioredoxin." (PMID 28146117, 2017). "In this study, we found that sirtinol (SIRT1 inhibitor) could block the inhibitory effect of losartan on the UUO-induced renal fibrosis, suggesting that the anti-fibrotic function of losartan might be mediated at least in part through the inhibition of ER stress via the up-regulation of SIRT1." (PMID 28146117, 2017). "SIRT1 induces deacetylation and deactivation of SMAD3 and SMAD4, thereby inhibiting the profibrotic response of TGF- β1 in vitro and in vivo models of renal fibrosis." (PMID 40514411, 2025). "Both SIRT1 and SIRT2 are nicotinamide adenine dinucleotide (NAD) dependent protein deacetylases, which can deacetylate Smad to improve renal fibrosis, and Sirt1 can be activated by resveratrol." (PMID 39866837, 2025). "Renal histopathological analyses reveal progressive exacerbation of renal fibrosis, lipid accumulation, inflammatory indicators, and JAML/Sirt1 signaling pathway abnormalities correlating with disease severity." (PMID 40837398, 2025). "SRT1720 activates Sirt1 and has been reported to reduce p65 acetylation, enhance autophagy in HG-induced podocyte EMT, reverse renal fibrosis, and improve renal function." (PMID 38347622, 2024). "Mechanistically, SIRT1 impedes the acetylation of histone H3K27 at the ACLY promoter, thereby suppressing FAO activity and promoting renal fibrosis." (PMID 39335456, 2024). "We used Western blot to investigate the involvement of SIRT1 and GPX4 in the progression of renal fibrosis." (PMID 39872048, 2024). "SRT1720, a Sirt1 activator, has been shown to decrease p65 acetylation, promote autophagic processes in high glucose-induced podocyte EMT, alleviate renal fibrosis, and restore kidney function." (PMID 39911234, 2024). "It upregulated the expression of Sirt1 and inhibited the TGF-β/Smad3 pathway, thus significantly and markedly improving renal fibrosis and renal function." (PMID 39687299, 2024). "For example, studies have shown that the inhibition of SIRT1 and SIRT2 with Sirtinol in the UUO model alleviated renal fibrosis." (PMID 39335456, 2024). "For example, rhein has been shown to mitigate renal fibrosis and correct FAO dysfunction by modulating the SIRT1/STAT3/Twist1 axis." (PMID 39911234, 2024). "The activation of SIRT1 has been shown to inhibit TGF-β/Smad3 signaling, thereby reducing Smad3 acetylation and improving renal fibrosis in 5/6 nephrectomized rats." (PMID 38074159, 2023). "FMN upregulated SIRT1 expression to activate the Nrf2/ARE signaling pathway and ameliorated oxidative stress in DN to prevent the progression of renal fibrosis." (PMID 37483618, 2023). "Experiments on the db/db mice have demonstrated that formononetin can improve renal oxidative stress and prevent the progression of renal fibrosis by activating the Nrf2-ARE signal pathway and increasing SIRT1 levels." (PMID 37954274, 2023).
renal fibrosis (continued). "Another study with rat epithelial cells demonstrated that resveratrol stimulated SIRT1 to deacetylate SMAD3, which reversed the TGF-β1-induced upregulation of type IV collagen and fibronectin mRNA levels to attenuate renal fibrosis." (PMID 35277012, 2022). "For instance, treatment with the SIRT1 activator SRT1720 in UUO model mice increased COX-2 expression and attenuated renal fibrosis and inflammation." (PMID 35277012, 2022). "SIRT1 upregulates the expression of NRF2 and activates the antioxidant response element (ARE) antioxidative pathway to prevent the progression of renal fibrosis." (PMID 35277012, 2022). "SIRT1 overexpression abolishes TGF-β1-induced kidney cell apoptosis and renal fibrosis, via suppression of CTGF expression." (PMID 35795148, 2022). "SIRT1 and SIRT3 can exert protective effects against renal fibrosis by inhibiting inflammatory responses and apoptosis, and by regulating energy metabolism." (PMID 36148005, 2022). "In mice, SIRT1 agonists attenuated RLDC-induced chronic inflammation, tissue damage, and renal fibrosis." (PMID 35874713, 2022). "There is an inverse relationship between SirT1 and the TGF-β signaling pathway in renal fibrosis, and SirT1 has the effect of counteracting renal fibrosis." (PMID 35408745, 2022). "To investigate the potential roles of SIRT1 in kidney lesions, we bred UUO model mice, which are known to be suitable subjects in which to induce renal fibrosis." (PMID 33758176, 2021). "We revealed that C. cicadae upregulates SIRT1/FOXO3a expression, suppresses oxidative stress, decreases ECM accumulation, and controls autophagic stress, which in turn inhibits renal fibrosis and ameliorates hypertensive renal injury." (PMID 35222012, 2021). "Collectively, our data demonstrated that FMN up-regulated the expression of Sirt1 to activate the Nrf2/ARE signaling pathway, improved oxidative stress in DN to prevent the progression of renal fibrosis." (PMID 33519483, 2020). "It was reported that miR-122 and Sirt1 suppressed TGF-β signalling to affect liver cancer metastasis and ameliorate renal fibrosis, respectively." (PMID 31195981, 2019). "Therefore, it is plausible that increased SIRT1 activity may also attenuate renal fibrosis in DKD." (PMID 30386303, 2018). "Our study demonstrated that Sirt1 inhibits renal fibrosis at least partially by inhibiting AT1R and NF-κB expression, and previous studies also supported that Sirt1 inhibits renal fibrosis by inducing COX2, deacetylating Smad3 and STAT3." (PMID 27659793, 2016). "In recent years, studies have reported that SIRT1 not only interacts with JMJD3 to inhibit macrophage polarization and SASP production, exerting mitochondrial protection and anti-renal fibrosis effects, but also interacts with TEAD1 to improve mitochondrial function and alleviate kidney injury." (PMID 40552151, 2025). "Taken together, our data suggested that DSI protected renal fibrosis against ferroptosis may be partially via SIRT1/GPX4 activation, highlighting that the potential effects of DSI as a novel therapeutic drug for limiting renal fibrosis." (PMID 39872048, 2024). "SIRT1 modulates inflammation through various signaling pathways, including NF-κB, HIF-1α, HMGB1, PPAR, and AMPK, which play crucial roles in the pathogenesis of renal fibrosis." (PMID 39335456, 2024). "Molecular docking has demonstrated that isoliquiritigenin binds directly to Sirt1 and regulates the MAPK and Nrf-2 signalling pathways to neutralise inflammatory responses and oxidative stress and reverse the deterioration of renal function and renal fibrosis." (PMID 38347622, 2024). "The class III HDAC family members currently thought to be associated with the development of renal fibrosis mainly include SIRT1 and SIRT2; there is no consensus on the role of SIRT1 in renal fibrosis." (PMID 36148005, 2022).
renal fibrosis (continued). "SIRT1 reverses Smad3 acetylation and thereby inhibiting the profibrotic response of TGF-β1 in vitro and in vivo such as in unilateral-ureteric obstruction mouse model of renal fibrosis." (PMID 35795148, 2022). "Interestingly, in an unexpected finding, resveratrol interacted with both SMAD3 and SMAD4 simultaneously to prevent the formation of the SMAD3/4 complex via SIRT1, inhibiting SMAD3 phosphorylation and renal fibrosis." (PMID 35277012, 2022). "Studies have shown that inhibition of miRNAs can reduce EMT and renal fibrosis in HK-2 cells of diabetic OLETF rats, and SIRT1 is identified as the target of these two miRNAs, speculating that SIRT1 has a regulatory effect on OLETF rates DKD model." (PMID 35774140, 2022). "This study reveals the protective role of the SIRT1/HIF-2α axis in kidney fibrosis and CKD, which may provide a new target for the treatment of renal fibrosis and CKD." (PMID 33758176, 2021). "A single study on renal fibrosis confirmed Sirtuin-1 as a target of miR-133b in HK2 cells and showed that the inhibition of miR-133b expression resulted in the attenuation of TGF-β1-induced EMT and renal fibrosis through the upregulation of Sirtuin-1 expression." (PMID 33691785, 2021). "Via the miR-34a-5p/sirtuin 1 (SIRT1)/HIF-1α pathway, long intergenic noncoding RNA (lincRNA) 1700020I14Rik suppresses expression of renal fibrosis biomarkers, inhibits mesangial cell proliferation under diabetic conditions, and is involved in progression of DN." (PMID 33299464, 2020). "It has been reported that the protective effect of Sirt-1 against DN may attribute to inhibition of TGF-β/Smad cascade, inflammatory responses, renal fibrosis, and podocyte apoptosis, as well as prevention of mitochondrial dysfunction." (PMID 33049944, 2020). "In the present study, we aimed to investigate whether SSR could alleviate renal fibrosis by regulating NLRP3 inflammasome and Sirt1/Smad3 deacetylation pathway." (PMID 31118021, 2019). "To clarify whether the effect of 1700020I14Rik on renal fibrosis was the interaction with miR-34a-5p through Sirt1/ HIF-1α pathway, we firstly identified the effect of 1700020I14Rik on the expressions of Sirt1 and HIF-1α." (PMID 29700282, 2018). "We further investigated the in vivo effects of losartan with or without sirtinol (an inhibitor of SIRT1) on ER stress and renal fibrosis using a tunicamycin-induced ER stress mouse model and a unilateral ureteral obstruction mouse model." (PMID 28146117, 2017). "Experimental models have demonstrated that SIRT1 reduces albuminuria by preserving podocyte function, reduces oxidative stress, modulates the advanced glycation end products and receptor for advanced glycation end products (AGEs-RAGE) axis, and attenuates renal fibrosis." (PMID 41009597, 2025). "In a unilateral ureteral obstruction (UUO) mouse model, activation of Sirt1 signaling was accompanied by an increase in phosphorylated endothelial nitric oxide synthase (eNOS) levels, and Sirt1 interacted with eNOS to improve the UUO model for scoring renal fibrosis." (PMID 38347622, 2024). "Moreover, we found that AM and CZ significantly reduced renal fibrosis and inflammation in CKD rats, which may be related to the regulation of SIRT1/JNK signaling pathway." (PMID 37089928, 2023). "Therefore, the up regulation of SIRT1, SIRT3 and SIRT4 and downregulation of Claudin 1 by MR extract might prevent renal fibrosis by suppressing mitochondrial oxidative stress and the production of inflammatory cytokines." (PMID 35956936, 2022). "Therefore, SirT1, STAT3, Twist1 and Cpt1a may represent useful targets for the prevention of renal fibrosis." (PMID 35408745, 2022). "In addition, RKT treatment did not enhance the up-regulation of renal SIRT1 expression in response to UUO compared with the CTL group, and thus failed to improve renal fibrosis." (PMID 32024850, 2020).
Cerebral ischemia (101 papers, 2011 to 2026). Restriction of arterial blood supply to the brain associated with insufficient oxygenation to support the metabolic requirements of the tissue. "Research indicates that upregulation of miR-489-3p exacerbates neuronal apoptosis caused by cerebral ischemia-reperfusion injury through its targeting of Sirt1." (PMID 40160465, 2025). "Magnoflorine attenuated the cerebral ischemia-induced neuronal damage, which was possibly associated with antioxidative stress, suppression of autophagy, and activation of the Sirt1/AMPK pathway in the rats." (PMID 36124014, 2022). "Several studies have implicated a protective role of SIRT1 against various neurological disorders including cerebral ischemia." (PMID 33924243, 2021). "Interestingly, recent growing evidence suggests that the neuroprotective effects of SIRT1 are associated with autophagy regulation in the pathophysiological process of cerebral ischemia." (PMID 36507335, 2022). "Finally, we analyze the mechanisms and effects of SIRT1 in several common neuroinflammation-associated diseases, such as cerebral ischemia, traumatic brain injury, spinal cord injury, AD, and PD." (PMID 33014276, 2020). "Besides antioxidants, SIRT1 is linked to the oxidative stress response in cerebral ischemia." (PMID 30983970, 2019). "Sirtuin-1 (Sirt1) restores mitochondrial structure and function in rats by activating Sirt3 after cerebral ischemia/reperfusion injury." (PMID 41241701, 2025). "The regulation of the Sirt1/Nrf2 signaling pathway by sizing exerts a neuroprotective effect in cerebral ischemia-reperfusion through the inhibition of oxidative stress." (PMID 40160465, 2025). "Another ubiquitin-specific peptidase, USP7, has been shown to promote PINK1/Parkin-dependent mitophagy, thereby alleviating cerebral ischemia-reperfusion injury by deubiquitinating and stabilizing SIRT1." (PMID 40724883, 2025). "miR-489-3p has been identified as a key player in the regulation of Sirt1-mediated apoptosis in cerebral ischemia cells." (PMID 40160465, 2025). "Although numerous natural compounds, including resveratrol, curcumin, and icariin, have been confirmed to exert neuroprotective effects on cerebral ischemia through Sirt1 activation, further research is warranted." (PMID 40160465, 2025). "The ability of the SIRT1 inhibitor, EX527, to counteract these effects underscored the importance of the SIRT1–H4K16ac pathway in mediating the protective action of ANP against cerebral ischemia-reperfusion injury." (PMID 40724883, 2025). "Significantly, the protective impact on cerebral ischemia-reperfusion injury was weakened by the Sirt1 inhibitor EX-527 via modulation of the necroptosis signaling pathway." (PMID 40160465, 2025). "SIRT1 overexpression enhances the deacetylation of SIRT3, boosting its activity and improving neurological damage caused by cerebral ischemia-reperfusion injury and mitochondrial dysfunction." (PMID 40356977, 2025). "Our study demonstrated that SIRT1 overexpression increased the mitochondrial length and mitochondrial cristae number after cerebral ischemia, which were respectively reversed by SIRT1 interference." (PMID 38767771, 2024). "On the other hand, SIRT1 also represses autophagy in lung and cerebral Ischemia/Reperfusion (I/R) injury to suppress MEC apoptosis and inflammation." (PMID 39598406, 2024). "Diosmetin, a natural flavonoid, has been reported to inhibit oxidative stress through the SIRT1/Nrf2 signaling pathway and reduce brain ischemia/reperfusion injury." (PMID 38958365, 2024).
Cerebral ischemia (continued). "BYHWD inhibited cerebral ischemia/reperfusion injury by promoting angiogenesis through SIRT1/VEGF pathway." (PMID 37506135, 2023). "Taken together, Sirt1 can downregulate the inflammatory response after cerebral ischemia by directly or indirectly regulating NF-κB signaling pathway." (PMID 37622049, 2023). "Recent studies have confirmed the protection role of Sirt1 on the improvement of cerebral ischemia/reperfusion injury." (PMID 37650573, 2023). "Wan and colleagues reported that AMPK activator pretreatment reduces ATP energy consumption during cerebral ischemia by activating SIRT1, thus showing beneficial effects in protecting neurons." (PMID 37627275, 2023). "Sirt1 specific inhibitor EX527 notably weakened the neuroprotective efficacy of HGWD against cerebral ischemia, and significantly abolished its modulation on microglia polarization and synaptic plasticity in vivo." (PMID 37650573, 2023). "Sirt1 has been proved to play a neuroprotective role in cerebral ischemia by the anti-inflammatory properties." (PMID 36627572, 2023). "It was suggested that Snhg8/miR-425-5p/Sirt1/NF-κB axis plays a critical role in the regulation of cerebral ischemia-induced BBB damage." (PMID 37622049, 2023). "The neuroprotective effect of SIRT1 in the context of cerebral ischemia is mediated by multiple mechanisms." (PMID 37266433, 2023). "The results suggested that the inhibition of AMPK activity eliminated the neuroprotective effect of 14, 15‐EET on cerebral ischemia reperfusion via the AMPK/SIRT1/ FoxO1 signal pathway." (PMID 37017405, 2023). "Cycloastragenol, the active form of astragaloside IV from Radix astragali, upregulated Sirt1 expression and then suppressed neuroinflammation after brain ischemia." (PMID 37650573, 2023). "For example, the upregulated Sirt1 induced by cycloastragenol represses apoptosis and neuroinflammation following brain ischemia." (PMID 36627572, 2023). "SNHG12 targets miR-199a to upregulate SIRT1 expression, thereby attenuating cerebral ischemia/reperfusion injury through AMPK pathway activation." (PMID 36275741, 2022). "Here, in this review, we will first introduce the molecular mechanisms and effects of SIRT1 in cerebral ischemia and I/R injury." (PMID 36507335, 2022). "SIRT1 has protective effects against CNS diseases, including cerebral ischemia, Huntington’s disease, AD, and Parkinson’s disease." (PMID 35744955, 2022). "Taken together, accumulating evidence has favored a unique role for autophagy and SIRT1-mediated autophagy in the pathogenesis and management of cerebral ischemia and I/R injury." (PMID 36507335, 2022). "In animal models exposed to external stimuli, such as cerebral ischemia and exercise, SIRT1 was upregulated with the activation of AKT signaling cascades and pro-apoptotic caspase 3 expression." (PMID 35892563, 2022). "Here, we summarized molecular mechanisms and new findings of SIRT1 in different cerebral ischemia conditions below." (PMID 36507335, 2022). "The Snhg8/miR-425-5p/SIRT1/NF-κB axis plays a critical role in regulating cerebral ischemia-induced microglial inflammation and brain-blood barrier damage." (PMID 36275741, 2022). "Almost all SIRTs, especially SIRT1 and 3, have been found to be involved in the processes following cerebral ischemia." (PMID 36289696, 2022). "An experimental study based on a cerebral ischemia model showed that SIRT1, FOXO1, PGC-1α, Bax, and Bcl-2 protein expressions were significantly reduced after oxygen-glucose deprivation/reperfusion (OGD/R)." (PMID 36105479, 2022).